NSD2 (nuclear receptor binding SET domain protein 2)
Diseases named in the same sentence as NSD2 in open-access papers (continued):
Sharing a sentence is not in itself a finding about the gene and the disease.
lymph node metastasis (1 paper, 2020). "Both EZH2 and NSD2 expression were associated with pathological grade of tumor and lymph node metastasis." (PMID 33665162, 2020). "Both EZH2 and NSD2 expression strongly correlated with histological grade of tumor and lymph node metastasis." (PMID 33665162, 2020). "Both EZH2 and NSD2 protein expression correlated with pathological grade of tumor and lymph node metastasis; the high grade and positive lymph node involvement were associated with increased rate of positive EZH2 and NSD2 (P < 0.001, P = 0.003)." (PMID 33665162, 2020).
meningioma (1 paper, 2023). A generally slow growing tumor attached to the dura mater. "In the study, miR-3605-5p, miR-664b-5p, PNRC2, BTBD8, SLFN13, DGKD, NSD2, EXTL2, and BVES were closely corrected with the malignant progression of meningioma." (PMID 37024523, 2023).
neuroendocrine tumors (1 paper, 2026). "For example, NSD2 inhibition restores androgen receptor expression and re-sensitizes neuroendocrine tumors to enzalutamide." (PMID 41601922, 2026).
orofacial cleft (1 paper, 2021). A disorder of facial skeleton that is characterized by cleft lip and/or cleft palate that result in feeding, speech and hearing problems caused by failures during development. "Less frequent manifestations among patients carrying NSD2 pathogenic variants included a history of aspiration, cardiac and renal anomalies, neonatal jaundice, sleep disturbances, hearing loss, genital abnormalities, and orofacial clefts." (PMID 33941880, 2021).
pancreatitis (1 paper, 2024). Inflammation of the pancreas. "To investigate the biological function of NSD2 in the pancreas under the context of injury, we first applied a caerulein‐induced pancreatitis recovery model (RAP) to 8‐week‐old PK and PKN° mice (100 μg kg−1, 8 hourly injection/day)." (PMID 38889281, 2024).
renal carcinoma (1 paper, 2019). A carcinoma arising from the epithelium of the renal parenchyma or the renal pelvis. "In the current study, we found that the expression of NSD2 mRNA was extremely up-regulated in diverse types of renal cancer, particularly in metastatic ccRCC." (PMID 31692936, 2019). "The result suggested that the expression of NSD2 mRNA was elevated in diversified types of renal cancer except papillary RCC (pRCC)." (PMID 31692936, 2019). "In the present study, we found that NSD2 mRNA was significantly amplified in several types of renal cancer by bioinformatic analysis, especially in metastatic ccRCC samples." (PMID 31692936, 2019).
renal fibrosis (1 paper, 2022). A final common manifestation of a wide variety of chronic kidney diseases characterized by glomerulosclerosis and tubulointerstitial fibrosis. "Collectively, these results indicated that NSD2 can mitigate renal fibrosis and impairment in DN." (PMID 35354439, 2022). "The m6A RNA methyltransferase METTL3 can enhance NSD2 mRNA stability and expression by YTHDF1 to alleviate renal impairment and renal fibrosis in DN." (PMID 35354439, 2022).
cancer (100 papers, 2013 to 2026). A tumor composed of atypical neoplastic, often pleomorphic cells that invade other tissues. "Emerging evidence also implied that NSD2 is implicated in cancer progression of several solid tumors." (PMID 40097917, 2025). "Mutations in NSD1 and NSD2 are linked to developmental syndromes and cancer, highlighting their critical biological functions." (PMID 40586874, 2025). "NSD2 histone methyltransferase dimethylates the DNA packaging protein histone H3 at the 36th lysine residue (H3K36me2) and elevated NSD2 protein expression has been observed in various human cancers, often linked to tumorigenesis." (PMID 39351229, 2024). "NSD2 mal-expression has been linked with cancer development and proliferation, therefore it gained tremendous attention as a drug target for cancer management, especially in cases of AML." (PMID 39163297, 2024). "Inactivation of NSD2 entirely disrupted AR binding at over 65% of its tumor cistrome, importantly without affecting AR protein levels, and attenuated hallmark cancer phenotypes." (PMID 39251788, 2024). "Beside cancers, NSD2 is also linked with other diseases, such as inflammatory and autoimmune diseases." (PMID 39163297, 2024). "Overall, this study identified promising natural compounds as potential pharmaceutical agents in the treatment of NSD2-associated cancers." (PMID 39163297, 2024). "Accordingly, NSD2 inactivation attenuated hallmark cancer phenotypes that were fully reinstated upon exogenous NSD2 re-expression." (PMID 38464251, 2024). "NSD2 overexpression is linked to the aggressiveness of tumors and is involved in over 20 types of cancer." (PMID 39163297, 2024). "NSD2 is an oncoprotein that is aberrantly expressed, amplified, or somatically mutated in multiple types of cancer." (PMID 38516186, 2024). "On the contrary, NSD2 encodes a protein paralog of the lowest molecular weight, and its functions are implicated in cancers including multiple myeloma, endometrial cancer, hepatocellular carcinoma, and neuroblastoma." (PMID 37062069, 2023). "In particular, T1150A in NSD2 is one of the frequent somatic cancer mutants and the corresponding T1232A mutation in NSD3 has been shown before to be a driver mutant which increases cell proliferation and xenograft tumor growth." (PMID 37150325, 2023). "NSD2 overexpression is linked with tumor aggressiveness in cancers of the breast, cervix, lung, kidney, head and neck, brain, blood, colorectum, prostate, skin, and ovary." (PMID 35581654, 2022). "In general, the main hematopoietic tumors in which NSD2 mutations seem to play a significant role in cancer development or evolution are those described in the previous sections." (PMID 36232375, 2022). "NSD2 is one of the most frequently mutated epigenetic regulators in several cancer types, especially pediatric cancers." (PMID 36232375, 2022). "Regarding the implications of NSD2 loss-of-function in cancer, it has been reported that it can also have tumor suppressor functions controlling progenitor cell differentiation." (PMID 36232375, 2022). "Dimethylated histone H3 Lys36 (H3K36me2) regulates gene expression, and aberrant H3K36me2 upregulation, resulting from either the overexpression or point mutation of the dimethyltransferase NSD2, is found in various cancers." (PMID 34782608, 2021). "Second, aberrant upregulation of cellular H3K36me2 levels, induced by the overexpression or point mutation of NSD2, has been found in various cancers." (PMID 34782608, 2021). "The biological divergence and potential mechanistic differences in NSD2 associated with neurodevelopmental disorders and cancers remain undetermined." (PMID 33718354, 2021). "NSD2 is highly expressed in several types of cancers, and depletion of NSD2 causes growth retardation during development in mice." (PMID 32573059, 2020).
cancer (continued). "On the disease connections, we used a NSD2 gain-of-function model which led to the discovery of potential therapeutic implication of DNA inhibitors in the related cancers, while the other study only used NSD1 and DNMT3A loss-of-function models." (PMID 31814083, 2020). "Global correlation of gene expression levels between NSD2 and the cell cycle‐associated genes in various tissues and cancer cell lines suggested that NSD2 is implicated in cell cycle regulation in diverse cell types." (PMID 32573059, 2020). "Here we show that cancer-associated alterations in the expression the histone methyltransferase NSD2 can contribute to the formation of aberrant epigenetic domains that alter the expression of clusters of genes." (PMID 27604143, 2016). "Consequently, NSD2 inactivation abolishes hallmark cancer phenotypes, whereas its re-expression in deficient cells restores neoplastic features." (PMID 39251788, 2024). "Contrary to loss-of-function NSD1 mutations in cancers, which suggest a tumor suppressor function, NSD2 has emerged as an oncogenic gene with elevated expression or hyperactive mutations in multiple human cancers, including colorectal, prostate, and lung cancers." (PMID 37602556, 2023). "In addition, many missense variants of NSD1 and NSD2 were observed in various types of cancers like hematological cancers, head and neck squamous cell carcinomas, human brain tumor cell lines, and lung cancers." (PMID 37150325, 2023). "Therefore, our research provided a clue to how mutations of BRCA1 and NSD2 resulted in cancer transformation." (PMID 32826945, 2020). "Additionally, NSD2 knockdown significantly enhances the efficacy of cisplatin against OS cells and accordingly inhibits properties associated with cancer stem cells (CSCs)." (PMID 30683853, 2019). "Conceptually, inhibiting lysine demethylases (KDMs) specific for H3K36me2, such as FBXL10 and FBXL11, is a potential strategy for treating cancers associated with loss-of-function NSD1 mutations, and inhibiting NSD2 may be effective for NSD2-hyperactive cancers." (PMID 37602556, 2023). "NSD2 is also implicated in cancer progression via methylation of Aurora A, but our study is the first report of NSD2 as the downstream target of the Aurora A. A recent study also showed NSD2 could be phosphorylated by AKT pathway to promote its stability, which is consistent with our conclusion." (PMID 35389552, 2022). "Indeed, NSD2 gene, encoding two main isoforms, NSD2-long (1,365 amino acid) and NSD2-short (647 amino acid), was located at chromosome 4p16.3, which exhibits strong cancer relevance." (PMID 31692936, 2019). "However, while MEK and BRD4 inhibitors converge in the downregulation of genes associated with cancer-acquired super-enhancers, NSD2 inhibition affects the expression of clusters of genes embedded in megabase-scale regions marked with H3K36me2 and that contribute to the RAS transcription program." (PMID 27604143, 2016). "In several cancer cell lines with elevated NSD2 expression, NSD2 knockdown inhibits the WNT/β-catenin/TCF-4 pathway and its downstream cyclin D1 expression through reduced H3K36me3, leading to impaired cell cycle progression." (PMID 41301842, 2025). "NSD2 has been shown to play a role in cancer progression by regulating key oncogenes, such as cyclin D1 (CCND1), MYC proto‐oncogene, BHLH transcription factor (MYC), and BCL2 apoptosis regulator (BCL2), which contribute to cell survival and proliferation." (PMID 40386826, 2025). "Overall, these studies highlight distinct and opposing roles of NSD2 in anti-tumor immune regulation, which can depend on the cancer type and possibly the context." (PMID 40586874, 2025). "With the exception of the singular H3K36me3-depositing SETD2, which appears to unambiguously function as a tumor suppressor, the remaining H3K36 methyltransferases (NSD1, NSD2, NSD3, and ASH1L) are all implicated in or associated with various cancers." (PMID 39403928, 2024).
cancer (continued). "Despite considering NSD2 as a promising target in cancer therapy, the development of selective small molecule inhibitors for NSD2 has been challenging." (PMID 39163297, 2024). "In this research, we focus in discovering NSD2 inhibitors for cancer, as it is the most directly related and extensively investigated disease linked with NSD2 abnormalities compared to other diseases." (PMID 39163297, 2024). "Overall, these compounds show potential as anti-cancer agents targeting NSD2, Nonetheless, further experimental validation is warranted to affirm these conclusions." (PMID 39163297, 2024). "This research explores natural compounds as potential selective inhibitors for NSD2 in cancer treatment." (PMID 39163297, 2024). "Nuclear receptor binding SET domain protein 2 (NSD2) significantly contributes to the development of cancer, making it a promising target for cancer drug discovery." (PMID 39163297, 2024). "Given NSD2 inactivation resulted in disruption of the cancer-specific AR cistrome, we set out to phenotypically characterize NSD2-deficient PCa cells." (PMID 39251788, 2024). "Concordantly, a dual NSD1/2 PROTAC degrader, called LLC0150, showed selective potency in AR-dependent as well as NSD2-altered human cancers." (PMID 39251788, 2024). "NSDs activation, including NSD1, NSD2, and NSD3 has been found to be tightly associated with the occurrence and progression of different cancer types." (PMID 39163297, 2024). "Using tissue microarrays, these studies showed NSD2 protein to be elevated in cancer specimens, showing a stage-wise increase from primary to mCRPC or neuroendocrine PCa39,40." (PMID 39251788, 2024). "Why do NSD1 and NSD2, both of which deposite H3K36me2 at intergenic regions, have the opposite roles in cancer?" (PMID 37602556, 2023). "Epigenetic dysfunction is associated with cancer and developmental anomalies such as WHSC1 (MMSET/NSD2)." (PMID 37806494, 2023). "NSD2 is a histone methyltransferase, elevated NSD2 expression correlates with worse prognosis in a number of cancers due to its oncogenic role in promoting cell growth and metastases." (PMID 38062230, 2023). "While both NSD1 and NSD2 deposit H3K36me2, the roles of NSD1 and NSD2 in cancer appear to be distinct." (PMID 37602556, 2023). "NSD2 expression between tumor and normal tissues from patients with different cancers was analyzed using the TIMER2.0 database." (PMID 38062230, 2023). "In cancer cells, numerous somatic mutations were observed in critical epigenome regulators including the H3K36 dimethyltransferases NSD1 and NSD2." (PMID 37150325, 2023). "We observed similar cancer-specific H3K4me3-BDs associated with hijacking of super-enhancers of other common oncogenes in B cell (MAF, MYC, and FGFR3/NSD2) and T cell malignancies (LMO2, TLX3, and TAL1)." (PMID 34933939, 2022). "Here, we will focus on the normal and pathological functions of NSD2, which is involved in the initiation and relapse of a wide range of cancers." (PMID 36232375, 2022). "Existing studies have also proposed that NSD2 is important for Akt activation in different cancer cells." (PMID 34671018, 2021). "Contrarily, NSD2 silencing or inhibition efficiently inhibited the tumorigenesis and progression of different cancers." (PMID 34671018, 2021). "NSD2 silencing sensitized cancer cells to combinatorial treatment with a phosphoinositide 3-kinase (PI3K) inhibitor and DNA-damaging agent." (PMID 34671018, 2021). "NSD2 alternative splice isoforms in cancers, in particular, have received substantial attention as of late." (PMID 33718354, 2021). "Nevertheless, NSD2 was overexpressed in patients with advanced cancer, who had poorly differentiated tumors, and its levels were higher than in normal epithelia." (PMID 34944712, 2021). "The protein expression levels of EZH2 and NSD2 in benign lesions were significantly lower than that in cancers." (PMID 33665162, 2020).
cancer (continued). "TCGA database revealed that NSD2 and BRCA1 had a number of common mutations in different types of cancers and they have been accumulated in cancer cell." (PMID 32826945, 2020). "Two histone methyltransferases, enhancer of zeste homolog 2 (EZH2) and nuclear SET domain-containing 2 (NSD2), are aberrantly expressed in several types of human cancers." (PMID 33665162, 2020). "NSD2 is upregulated in some cancers and cancer models where it promotes somatic reprogramming and transformation." (PMID 33287230, 2020). "For instance, NSD2’s E1099 is located in its SET-I motif and its E1099K mutant was characterized as a hot-spot cancer mutation with the gain-of-activity of H3K36 methylation." (PMID 31081496, 2019). "NSD2/WHSC1 thus emerged as a new relevant druggable target in MCL and other cancers with recurrent gene mutations." (PMID 31500350, 2019). "Previous studies have manifested that aberrant expression of NSD2 would regulate EMT in diverse cancers 7-9." (PMID 31692936, 2019). "Combinatorial therapies using MEK inhibitors or BRD4 inhibitors together with NSD2 inhibition are likely to be effective in fighting RAS-dependent cancers with NSD2 overexpression." (PMID 27604143, 2016). "NSD2 may play a critical role in the development and prognosis of human cancers and may represent a new therapeutic target for human solid tumors." (PMID 38400589, 2025). "Similarly, the gain-of-function NSD2 E1099K with elevated H3K36me2 levels activates gene expression program associated with oncogenic KRAS signaling, thus promoting malignant tumor progression in lung adenocarcinoma (LUAD)." (PMID 41301842, 2025). "The function of NSD2 in cancer progression is largely dependent on its enzymatic activity." (PMID 40097917, 2025). "If this model could be validated in follow-up studies in cancer cells, an NSD2 inhibitor would be a therapeutic option for T1150A containing patients." (PMID 37150325, 2023). "Moreover, we and others have demonstrated NSD2 EK activates a transcriptional program that is highly cell-context dependent, possibly endowing cancer cells with a broad repertoire of pathways needed to navigate the selective pressures of therapy." (PMID 37016431, 2023). "The high expression of NSD2 has also been detected in a variety of malignant tumors." (PMID 37959819, 2023). "Additionally, NSD2 was reported to be phosphorylated and stabilized by Akt kinase, and epigenetically regulate Rictor to promote cancer metastasis, indicating that NSD2 exerts context-dependent effects." (PMID 35069527, 2021). "Interestingly, research has shown that NSD2 is an important oncogene that drives the development of multiple cancers by catalyzing histone-lysine methylation and disrupting chromatin integrity." (PMID 34271943, 2021). "Indeed, in both mouse and human tissues and human cancer cell lines, the expression levels of NSD2 were positively correlated with those of cell cycle‐related genes." (PMID 32573059, 2020). "In addition, the NSD2 is highly expressed in several cancers, including CRC, when compared to their normal counterparts." (PMID 32153656, 2020). "NSD2: mRNA overexpressed is necessary for cancer initiation?" (PMID 32153656, 2020). "Inhibition of NSD2 sensitized cancer cells to PI3K inhibitors and DNA-damaging agents." (PMID 31500350, 2019). "Over the past decade, increasing evidence has revealed that NSD2 may be involved in epithelial-mesenchymal transition (EMT) in cancer metastasis." (PMID 31692936, 2019). "In fact, NSD2 has been linked to constitutive activation of NF-kB signaling in CRPC, promoting cancer cell proliferation and survival via an autocrine positive loop in which NSD2 expression is in turn stimulated by inflammatory cytokines, such as TNFα and IL-6, via NF-kB." (PMID 29888169, 2018).